FLT3 (fms related receptor tyrosine kinase 3)
Diseases named in the same sentence as FLT3 in open-access papers (continued):
Sharing a sentence is not in itself a finding about the gene and the disease.
acute leukemia (continued). "Consistent with the FLT3-ITD+ Ba/F3 cells, increased levels of the p21 protein were also observed in FLT3-ITD+ MV4-11 human acute leukemia cells compared to RS4;11 cells expressing wild-type FLT3." (PMID 27387666, 2016). "Armstrong and co-authors revealed that FLT3 gene overexpression is the most distinctive feature of MLL rearranged acute leukemia." (PMID 27391351, 2016). "Due to the strong activity against FLT3 Lestaurtinib was first clinically studied in acute leukemia, with a considerable response rate of 27%." (PMID 25504435, 2014). "According to all these observations, it was suggested that additional cooperative events were required in addition to FLT3-ITD to progress to acute leukemia." (PMID 23936658, 2013). "The highest cytotoxic potential against T-ALL cell lines and patient lymphoblasts was displayed by NVP-BAG956, a dual PI3K/PDK1 inhibitor which has been shown to be effective against BCR-ABL- and mutant FLT3-expressing acute leukemia cells." (PMID 22885370, 2012). "As a therapeutic target, FLT3 is appealing since it is up-regulated in a significant number of acute leukemias and its protein expression is restricted to primitive and immature hematopoietic progenitors." (PMID 21272320, 2011). "Overexpression of FLT3 may lead to its activation as a receptor and serve as a prognostic marker in pediatric acute leukemia." (PMID 39273530, 2024). "Targeting the FMS-like tyrosine kinase receptor-3 (FLT3) in acute leukemia is mainly important." (PMID 36407352, 2022). "Increased ROS production by the NADPH oxidase (NOX) family of enzymes in acute leukemias, particularly FLT3-ITD AML, has been increasingly studied over the last few years, and highlights that elevated ROS is a mechanism conferring survival advantages in FLT3-mutant AML." (PMID 36536316, 2022). "The NCCN (National Comprehensive Cancer Network) guidelines recommend a screening lumbar puncture (LP) to assess for CNS involvement in asymptomatic patients with monocytic AML, mixed phenotype acute leukemia, extramedullary disease, WBC >40 × 109/L, or presence of FLT3 mutations." (PMID 34588432, 2021). "However, progression to acute leukemia with the ETP-ALL phenotype requires acquisition of other driver mutations, such as FLT3-ITD and NRAS, that lead to dysregulation of pathways regulating cellular proliferation and apoptosis." (PMID 34912707, 2021). "FLT3 is a cytokine receptor that is expressed on the leukemic blasts in acute leukemia." (PMID 31518054, 2019). "The expression of the FLT3-ITD mutation in mouse models is sufficient for the development of fatal myeloproliferative neoplasm, although an extra genetic “hit” is required for the development of acute leukemia." (PMID 30332834, 2018). "Another such possible target in pediatric acute leukemia is FMS-like tyrosine kinase 3 (FLT3)." (PMID 25295230, 2014). "In conclusion, our work underlines the necessity of the detection of the FLT3-ITD mutation in APL, that constitutes a separate entity of a worse prognosis and where new treatment strategies are necessary in order to decrease early mortality in an otherwise highly curable form of acute leukemia." (PMID 22742960, 2012). "While the FLT3/ITD mutation alone induces a lethal myeloproliferative neoplasm (MPN) and the Nup98-HoxD13 translocation alone produces a myelodysplastic syndrome (MDS), mice bred to express both mutations develop an acute leukemia with short latency and 100% penetrance." (PMID 22643831, 2012). "Currently, emerging molecular targeted therapy is being used in clinic, such as inhibitors of FMS-like tyrosine kinase 3 (FLT3) and mammalian target of rapamycin (mTOR) in acute leukemia." (PMID 29456860, 2018). "These initial observations indicated that FLT3-ITD mutant is sufficient to induce a myeloproliferative disorder, but it was unable to develop an acute leukemia recapitulating the phenotypic features observed in humans." (PMID 23936658, 2013).
acute leukemia (continued). "We previously generated a knock-in mouse, harboring an internal tandem duplication at the endogenous Flt3 locus, which develops a fatal myeloproliferative neoplasm (MPN), but fails to develop acute leukemia, suggesting additional mutations are necessary for transformation." (PMID 27636998, 2016). "FLT3 abnormalities are negative prognostic markers in acute leukemia." (PMID 27391351, 2016). "Given the importance of both the activation loop and SHP2 in FLT3-ITD-mediated transformation, the development of drugs that interfere with binding of SHP2 to Y842 or with the activity of SHP2 could be useful drugs for the treatment of patients with acute leukemia." (PMID 28271164, 2017). "It has been reported that either KMT2A-PTD or Flt3-ITD do not develop AML; however, the cooperation of Flt3-ITD with Kmt2a-PTD developed acute leukemia in a mouse model." (PMID 32015320, 2020). "Besides, to evaluate the efficacy of sorafenib on FLT3-negative acute leukemia, we are doing a multi-center, randomized, phase 3 trial of sorafenib maintenance after allo-HSCT in patients with FLT3-negative acute leukemia (NCT04674345)." (PMID 40830801, 2025).
myeloproliferative neoplasm (59 papers, 2009 to 2025). A clonal hematopoietic stem cell disorder, characterized by proliferation in the bone marrow of one or more of the myeloid (i.e., granulocytic, erythroid, megakaryocytic, and mast cell) lineages. "Only recently, it became known that, in mice with artificially induced myeloproliferative disease after injection of hematopoietic myeloid stem progenitors carrying the flt3-itd mutation, an increase in N-MYC oncogene expression was found." (PMID 37606386, 2023). "In vivo myeloproliferative diseases induced by FMS like tyrosine kinase 3-internal tandem duplications (FLT3-ITD), a mutation present in approximately 30% of AML patients, were compromised by deletion of SHP-1." (PMID 34490276, 2021). "Mutation of the FLT3-ITD residue that recruits SHP-2 also reduced FLT3-ITD-induced myeloproliferative disease in vivo." (PMID 34490276, 2021). "Further support for our results comes from the finding that an activating mutation in Flt3 leads to the development of a myeloproliferative disorder 73 that is characterized by increased numbers of GMPs and an accumulation of mature myeloid cells 74–76." (PMID 25100642, 2014). "A knock-in mouse model by inserting an internal tandem duplication mutation into the JM domain of murine FLT3 developed the myeloproliferative disease (characterized by splenomegaly and leukocytosis with myeloid lineage cell expansion) by inserting an ITD mutation into the JM domain of murine FLT3." (PMID 36072760, 2022). "These experiments showed that FLT3-ITD expressing bone marrow cells caused a myeloproliferative disease in the recipient mice, characterized by splenomegaly, leukocytosis and expansion of myeloid lineages, but without developing an AML phenotype similar to human patients." (PMID 28538663, 2017). "The essential fusion of FLT3 (Fms Related Receptor Tyrosine Kinase 3) and MYO18A (Myosin 18 alpha) was detected in eosinophilic granulocytes associated with chronic myeloproliferative disorders, such as atypical chronic myeloid leukemia." (PMID 37691828, 2023). "DNA methyltransferase 3a (Dnmt3a) haploinsufficiency, however, transforms Flt3-ITD mutant murine myeloproliferative neoplasms (MPNs) into AML." (PMID 34903841, 2022). "One FLT3 mutant was found to activate Rho kinase through activation of RhoA small GTPase, resulting in myeloproliferative disease development." (PMID 34811450, 2021). "Heterozygous and homozygous FLT3-ITD knockin mice develop a myeloproliferative disorder resembling chronic myelomonocytic leukemia (CMML)." (PMID 34944812, 2021). "Most patients had high-risk features, including pre-existing myelodysplastic syndrome or myeloproliferative neoplasm (MDS or MPN, 41%), FLT3-ITD mutations (13%), and older age (median 71 years)." (PMID 33251145, 2020). "In a bone marrow transplant model, a fatal myeloproliferative neoplasm occurred, while in a knock-in FLT3–ITD model, a less severe human chronic myelomonocytic leukemia like disease resulted." (PMID 33042924, 2020). "FLT3–ITD expression originated a myeloproliferative disorder having different phenotypes and severity depending on the murine model." (PMID 33042924, 2020). "Here we report two cases with FLT3 fusions in patients demonstrating mixed features of myelodysplastic/myeloproliferative neoplasms." (PMID 30559310, 2018). "Genetic rearrangements involving FLT3 are rare and only recently have been detected in myeloid/lymphoid neoplasms associated with eosinophilia (MLN-eos) and chronic myeloproliferative disorders." (PMID 30559310, 2018). "Consistent with this, ectopic PIM2 expression induced resistance to FLT3 inhibition in both FLT3-ITD–induced myeloproliferative neoplasm and AML models in mice, underscoring the role of PIMs in the emergence of this phenotype." (PMID 29682194, 2018). "In this study, we have analyzed the possible role of the Myc network in Flt3-ITD-induced myeloproliferative disease." (PMID 30420889, 2018).
myeloproliferative neoplasm (continued). "In our case, this was possible by establishing BM chimeras with E15 FL cells, at which time the number of LSKCD150+48− cells was unperturbed, likely because this is before the development of overt myeloproliferative disease in Flt3-ITD mice." (PMID 28637883, 2017). "FLT3-ITD, NPM1, and DNMT3A mutations frequently occurred in AML patients and have been found conferred with myeloproliferative neoplasms in mouse model." (PMID 24895580, 2014). "The expression of FLT3-ITD from an endogenous promoter into a murine knock-in model resulted in the development of a myeloproliferative disorder characterized by myeloid progenitor expansion." (PMID 23936658, 2013). "Similarly, the reactivation of PTPRJ’s PTP activity by blocking ROS has been demonstrated to prolong survival in a murine model of FLT3 ITD–driven myeloproliferative disease." (PMID 36452504, 2022). "Both proteins are crucial downstream effectors of tyrosine kinase oncogenes (TKO) such as Fms-like receptor tyrosine kinase 3 with internal tandem duplications (Flt3-ITD), BCR-ABL and JAK2V617F which cause AML, CML and other myeloproliferative diseases (MPD), respectively." (PMID 31861239, 2019). "Similarly, LT-HSCs (LSKCD150+48−) were reported to be present in normal numbers in Flt3-ITD fetal livers before the onset of myeloproliferative disease." (PMID 30420889, 2018). "The Flt3-ITD mouse has a myeloproliferative disease with expanded myeloid populations." (PMID 30420889, 2018). "Homozygous FLT3-ITD/ITD (ITD/ITD) mice develop myeloproliferative disease after a long latency." (PMID 29416774, 2018). "While not as well-characterized, FLT3-TKD mutations also induce myeloproliferative disease in mice, but with a less aggressive phenotype compared to FLT3-ITD carriers." (PMID 30332834, 2018). "However, we here show that LT-HSCs decrease in favor of MPPs in Flt3-ITD mice which has developed a myeloproliferative disease, which has also been shown in other reports." (PMID 30420889, 2018). "In addition, activated PTPRJ was shown to inhibit cell transformation in vitro and extend survival of mice in the 32D cell/C3H/HeJ mouse model of FLT3 ITD–driven myeloproliferative disease." (PMID 28858244, 2017). "In addition, A674563 exhibited strong binding to ROCK1 kinase as well, which has been implicated to play roles in the c-KIT, FLT3 and BCR-ABL oncogenes mediated myeloproliferative diseases." (PMID 27074558, 2016). "Mice receiving a transplant of FLT3-ITD overexpressing bone marrow cells develop a myeloproliferative disorder (MPD)/ myeloproliferative neoplasm (MPN)." (PMID 34944812, 2021). "The findings of both dysplastic and proliferative features in the Flt3+/ITD/Wt1+/R394W mice are compatible with a myelodysplastic disorder/myeloproliferative neoplasm (MDS/MPN)." (PMID 30450160, 2018). "Furthermore, in a mouse bone marrow transplantation model, FLT3-TKD not only manifested a malignancy with longer latency compared to FLT3-ITD, but it was also found to cause an oligoclonal lymphoid disease, in contrast to FLT3-ITD, which led to the development of a myeloproliferative disorder." (PMID 28538663, 2017). "In contrast to the first model, in which FLT3 retroviral transduction likely resulted in overexpression of FLT3, the majority of these knock-in mice did develop myeloproliferative neoplasms (MPN), albeit with a less aggressive phenotype than the FLT3-ITD mice." (PMID 25295230, 2014). "In mice, knock-in of FLT3-ITD or FLT3-TKD, as well as NRAS p.G12D and KRAS p.G12D, induced a myeloproliferative neoplasm, and an AML phenotype was obtained by combination with other variants." (PMID 36499582, 2022). "SYK is indispensable for myeloproliferative disease development and its transformation to AML and a critical regulator of FLT3-ITD driven neoplasia due to its role in FLT3 transactivation." (PMID 31992353, 2020).
myeloproliferative neoplasm (continued). "A single genetic mutation in FLT3-ITD causes gradual myeloid cell expansion as in a myeloproliferative neoplasm (MPN), but does not cause the full development of AML." (PMID 30987263, 2019). "Spleen tyrosine kinase (SYK) is an obligatory signaling partner for FLT3 that is required for transformation to AML and necessary for myeloproliferative disease (MPD) development." (PMID 28881711, 2017). "miR-155 promotes FLT3-ITD-induced myeloproliferative disorder through inhibition of the interferon (IFN) response, inositol 5-phosphatase 1 (SHIP1), CEBPB, and PU.1, while it is upregulated in FLT3-ITD+ and MLL-rearranged AML." (PMID 29441324, 2017). "In contrast in mice, Flt3 transcripts and FLT3 protein were detected in the LT-HSC compartment suggesting a previously unrecognized role of FLT3 in LT-HSC homeostasis and establishes an intrinsic link between normal stem cell quiescence/homeostasis and development of myeloproliferative neoplasm." (PMID 33003568, 2020). "Flt3+/ITD mice are well characterized and develop a fatal myeloproliferative neoplasm (MPN)." (PMID 30450160, 2018). "Patients suffering from myeloproliferative disorders under treatment regimens that included KIs with molecular targets other than FLT3 inhibition did not report significant clinical responses and parameters of survival and disease progression were generally poor." (PMID 34683897, 2021). "UPN09 was diagnosed with secondary AML (prior diagnosis of myeloproliferative neoplasm (MPN); AML not otherwise specified (NOS), AML without maturation, normal male karyotype, no BCR–ABL1 fusion, no CEBPA, FLT3, or NPM1 mutation) in 2008." (PMID 34950586, 2021). "Flt3+/ITD mice develop a fatal myeloproliferative neoplasm (MPN) at a mean latency of 10 months, but do not independently develop myeloid leukemia." (PMID 30450160, 2018).
myelodysplastic syndrome (55 papers, 2009 to 2025). A clonal hematopoietic disorder characterized by dysplasia and ineffective hematopoiesis in one or more of the hematopoietic cell lines. "TP53multihit and FLT3 mutations have also been identified as top genetic predictors of adverse outcomes in the Molecular International Prognostic Scoring System for Myelodysplastic Syndromes." (PMID 37591941, 2023). "Studies examining specific AML subtypes have demonstrated deregulated β-catenin and/or merit in targeting the molecule in normal karyotype, FLT3 mutant, del(5q), myelodysplastic syndrome (MDS) related, core binding factor (CBF) mutated, and PML-RARα+ AML." (PMID 35352805, 2022). "In a phase II study of midostaurin monotherapy, 14 out of 20 patients with relapsed/refractory AML or myelodysplastic syndrome with FLT3 activating mutations achieved approximately 50% reduction in peripheral blasts." (PMID 30332834, 2018). "FLT3/ITD mutations also occur in 5% of patients with myelodysplastic syndrome (MDS)." (PMID 22970245, 2012). "Deregulated Wnt signalling contributes to the development of several AML subtypes including normal karyotype, FLT3-mutant, del(5q)+, myelodysplastic syndrome (MDS)-related, CBF-mutated, and PML-RARα+." (PMID 40301545, 2025). "Albeit uncommon in myelodysplastic syndromes (MDS), increased frequencies of FLT3 mutations are associated with MDS progressing to secondary AML." (PMID 33003568, 2020). "In contrast, the TET2, FLT3, RUNX1, BCOR and spliceosome mutations were more common in the IDO1-high group, which were commonly enriched in myelodysplastic syndrome (MDS)-transformed AML." (PMID 40234305, 2025). "While the prognostic impact of RAS mutations remains debated, their acquisition or clonal expansion, much like FLT3 mutations, is frequently observed during the transition from myelodysplastic syndromes (MDS) to AML, typically correlating with a poor prognosis." (PMID 41280924, 2025). "The phase IIB trial of midostaurin for wild‐type or mutated FLT3 AML and high‐risk myelodysplastic syndrome (MDS) showed that the rate of reduction in peripheral blood or bone marrow blasts by ≥50% was 71% in patients with FLT3‐mutant and 42% in patients with FLT3 wild‐type." (PMID 36254250, 2022). "In the open-label phase I/II trial, patients of any age receiving first-salvage treatment for FLT3-ITD AML or age > 60 years with untreated myelodysplastic syndrome or AML were treated with quizartinib plus azacitidine or low-dose cytarabine (LDAC)." (PMID 35681786, 2022). "Phase I studies have shown feasibility of adding the CXCR4 antagonist Plerixafor to sorafenib and GCSF in FLT3-mutated R/R AML, or to high-dose cytarabine and etoposide in pediatric patients with acute leukemias or myelodysplastic syndrome (MDS)." (PMID 35083154, 2021). "A multi-center phase I study was also initiated in patients with refractory or relapsed AML or myelodysplastic syndrome (MDS) as FLT-3 is an obvious therapeutic target of ABT-869." (PMID 19642998, 2009). "In frame internal tandem duplications (ITD), in the juxta-membrane part of Flt3, account for 25–35% of the mutations in AML and 5–10% of myelodysplastic syndrome (MDS) cases." (PMID 28498310, 2017). "The frequency of FLT3-ITD mutation varies according to the type of leukemia: it is found preferentially in AML but also detected at lower frequencies in myelodysplastic syndromes (MDS)." (PMID 38915455, 2024). "Related fields involved the following topics: leukemic transformation, clonal hematopoiesis (CH), myelodysplastic syndrome (MDS), and FLT3 study." (PMID 36119476, 2022). "Myelodysplastic syndromes (MDS) and AML are hematological malignancies associated with aberrant splicing patterns and FLT3 is one of the most mis-spliced genes in AML, dysregulation of the splicing process can also disturb apoptosis and cause resistance to therapies." (PMID 36316776, 2022).